LEP (leptin)
Diseases named in the same sentence as LEP in open-access papers (continued):
Sharing a sentence is not in itself a finding about the gene and the disease.
cancer (continued). "Chemical inhibitors targeting leptin signaling also alleviated the muscle-wasting phenotype, indicating that leptin signaling may be a new therapeutic target for cancer patients with muscle wasting." (PMID 30718259, 2019). "In this way, leptin overexpression may be relevant to fatigue and sleep disruption in cancer patients, through its inhibitory actions on HO neurons." (PMID 31773065, 2019). "Moreover, inhibition of leptin-induced NLRP3 inflammasome prevented cancer cell proliferation of MCF-7 breast cancer cells." (PMID 31141984, 2019). "This action of leptin remodeling the tumor microenvironment has been increasingly studied, due to its great importance establishing low grade inflammation in obese individuals, increasing the risks of cancer." (PMID 31262098, 2019). "Consistently, when ASCs and H295R cells were co-cultured, the increased expression of leptin and Ob-R in adipose and tumor cells respectively, might suggest the activation of a specific cancer promoting axis." (PMID 31817072, 2019). "There are also numerous reports that leptin is also involved in other cancers." (PMID 30718259, 2019). "However, these mouse models exhibited defective mammary gland development, representing a bias for studying the specific involvement of leptin in obese-induced cancers." (PMID 30634494, 2019). "Therefore, leptin-mediated signaling pathways play an important role in cancer cell proliferation, invasion, and metastasis." (PMID 31119158, 2019). "Leptin potently affects metaplasia and cancer cell proliferation." (PMID 31141984, 2019). "However, except in a few cancer types, such as breast, prostate, and colorectal cancers, the role of leptin in other tumors, such as lung and liver cancer is controversial and warrants further studies to provide a conclusive result." (PMID 30803210, 2019). "In TPC-1 and K1 cells, prolonged treatment with leptin (500 ng/ml for 96 h) resulted in a mild increase in the proliferation (about 20% over control only in K1 cells, p < 0.05) and in the migration of both cancer cell lines." (PMID 30906321, 2019). "Adipokines such as leptin could therefore be involved in CSCs-induced resistance to anti-cancer treatment, especially in overweight patients." (PMID 31756890, 2019). "Therefore, the role of leptin, and other adipokines on immunological response in cancer therapy should be considered in future studies." (PMID 31380268, 2019). "Thus, leptin and adiponectin can have either pro and anti-apoptotic activity depending on the system studied; in cancer, however, leptin has significant anti-apoptotic and adiponectin has pro-apoptotic actions." (PMID 29587359, 2018). "Leptin also induces the expression of TFs associated with the maintenance of the cancer stem cell phenotype, such as NANOG, SOX2, and OCT4 in a STAT3-dependent manner, promoting a more aggressive phenotype of cancer cells." (PMID 30404206, 2018). "Remarkably, leptin signaling induces the activation of these pathways in normal and cancer cells." (PMID 29719602, 2018). "In cancer, however, leptin promotes the “prone to live” state through anti-apoptotic activity." (PMID 29587359, 2018). "Notably, OB-R is expressed higher on tumor cells, where its binding to leptin induces cancer cell proliferation, migration, angiogenesis, and reduced apoptosis." (PMID 29719602, 2018). "Furthermore, the increased serum leptin and leptin receptor mRNA expression revealed the positive correlation with cancer recurrence and mortality in triple-negative breast cancer." (PMID 29682217, 2018). "Both leptin and TGFβ are secreted by adipose tissue, suggesting that FA metabolism in cancer cells may be regulated by the surrounding adipose tissue." (PMID 29996946, 2018). "Our findings indirectly indicate, however, that adipocyte-derived IL-6 and leptin might influence collagen reorganization, further promoting cancer metastasis, though confirmation of this hypothesis will require further experimentation." (PMID 30563531, 2018).
cancer (continued). "In addition to the variation in the experimental procedures, another possibility is that the leptin-mediated stimulatory or inhibitory effects are partly altered by other receptors in various types of cancer." (PMID 29682217, 2018). "Furthermore, the correlation of leptin and leptin receptor with cancer patient's survival outcome is listed." (PMID 29682217, 2018). "The results showed the relative leptin and leptin receptor expression in pan-cancer panel." (PMID 29682217, 2018). "This review mainly focuses on leptin-mediated effects and its downstream signaling related to the progression of cancers, and displays the clinical significance of this axis including the impact on cancer patient survival." (PMID 29682217, 2018). "Overexpression of leptin may result in extensive proliferation and, ultimately, prostate hyperplasia or cancer." (PMID 30186533, 2018). "In addition, leptin was found to potently induce the invasion of cancer cells in a matrigel invasion assay." (PMID 30510663, 2018). "Much more could be learned about the effects of these adipokines on various signaling factors in DS, and the cancer-related interactions of leptin and the anti-angiogenesis factors on chromosome 21." (PMID 29587359, 2018). "Understanding the role of leptin-related intracellular signalling pathways in tumour development could be helpful in early cancer detection." (PMID 30510663, 2018). "In addition, leptin can stimulate inflammatory response and promote the growth of some cancer cells." (PMID 29301582, 2018). "The cancer-stimulating activity of APP could act in synergy with similar activities of leptin, and the neuroprotective APP alpha secretase product could synergize with the neuroprotective activity of leptin." (PMID 29587359, 2018). "Additionally, the secreted leptin promotes EMT, a hallmark of cancer progression, metastasis, and chemoresistance." (PMID 29370782, 2018). "Hormonal factors such as insulin-like growth factor 1 (IGF-1) and leptin have been shown to be decreased by metformin administration and may potentially be responsible for the reduction of the cancer growth-supporting potential of patient sera." (PMID 29444159, 2018). "In addition to the original function in controlling appetite and energy expenditure, leptin-mediated signaling axis through leptin receptor is multifunctional which plays role in the regulation toward broad types of cancer." (PMID 29682217, 2018). "Cancer cells release leptin and express leptin receptor (LEPR), which suggests the potential leptin autocrine/paracrine signaling loop could affect tumor progression." (PMID 29682217, 2018). "For example, leptin is known to activate diverse signaling cascades, such as the JAK/STAT, MAPK, and PI3 kinase/AKT pathways, most of which are implicated in differentiation and proliferation of cancer cells." (PMID 29312618, 2017). "The adipokines leptin and adiponectin are known to affect multiple aspects of cancer progression." (PMID 29156726, 2017). "Moreover, several reports have shown a link between leptin signaling and the development of cancer stem cells and resistance to chemotherapeutics." (PMID 28659656, 2017). "Indeed, increased blood leptin levels have been clearly demonstrated to play a role in the development and progression of various types of cancers." (PMID 29312618, 2017). "Furthermore, activation of leptin signaling contributes to the development and/or progression of cancer through multiple mechanisms." (PMID 29312618, 2017). "Given the antagonistic intracellular effects of ADIPO and LEP in combination with the fact that a cancer cell will be exposed to both adipokines in vivo, the case for using the ADIPO:LEP ratio as a more accurate predictor of tumor growth microenvironment is supported by our results." (PMID 28873415, 2017).
cancer (continued). "The altered hepatic gene expression indicated a progressively increased protective effect of graded CR on cancer development, which is in agreement with a graded decrease in factors promoting tumor growth such as circulating leptin levels and fat mass in the same mice." (PMID 28768896, 2017). "Leptin's pleiotropic functions also involve angiogenic, inflammatory, and antiapoptotic effects, which are important for cells overexpressing OB-R, including cancer cells." (PMID 28659656, 2017). "Given that adiponectin exerts potent anti-tumor properties but leptin promotes tumor growth, changes in adiponectin and leptin levels could be attributed to high incidence of cancer in obese patients." (PMID 29312618, 2017). "Leptin suppressed apoptosis in cancer cells via autophagy induction and degradation of Bax." (PMID 29312618, 2017). "Moreover; curcumin, quercetin and EGCG have also been identified as targeting the JAK-STAT pathway, which is one of the main leptin signaling pathways, in several cancer cells." (PMID 28930270, 2017). "The TCF7L2 rs7903146 C>T, rs290481 T>C, LEP rs7799039 A>G, rs2167270 G>A and LEPR rs1137100 G>A, rs1137101 G>A and rs6588147 G>A polymorphisms were genotyped by SNPscan genotyping assays in 507 ESCC cases and 1,496 non-cancer controls." (PMID 29312594, 2017). "Furthermore, adipokines such as leptin or HGF can induce the secretion of various MMPs by cancer cells, thus indirectly promoting tumor invasion." (PMID 28915700, 2017). "Leptin is known to accelerate cell cycle progression in cancer cells." (PMID 29312618, 2017). "Additionally, we found that leptin increased its own receptor gene expression only in cancer cell lines." (PMID 28861689, 2017). "Moreover, OB-R and estrogen receptor (ER) are coexpressed in cancer indicating a possible interaction between leptin and estrogen systems to promote carcinogenesis." (PMID 28659656, 2017). "This interesting observation may suggest different biological pathways linking leptin and inflammation with cancer, which may involve sex‐specific biological and environmental factors." (PMID 26632325, 2016). "In addition, leptin signaling in cancer cells has been shown to inhibit apoptosis and promote cell division by suppressing p21 and up-regulating cyclin D, which controls the G1/S cell cycle checkpoint." (PMID 26751490, 2016). "Leptin signaling promotes cell migration and invasive potential in various cancer cell lines." (PMID 27036040, 2016). "The identified polymorphisms might assist in developing better risk-assessment tools, as well as generating novel targeted therapies, especially for obese cancer patients with impaired leptin and adiponectin signaling." (PMID 27768592, 2016). "Our study in a large multiethnic cohort did not observe an association between plasma leptin level and future cancer risk." (PMID 27636369, 2016). "Findings from population‐based studies for the link between leptin and cancer are scarce." (PMID 26632325, 2016). "Leptin-induced effects in cancer are linked to the activation of JAK/STAT signaling pathway, which is involved in the upregulation of Cyclin D1 and proliferation of cancer cells." (PMID 27472371, 2016). "Several studies indicate that leptin may be involved in carcinogenesis, cancer cell proliferation, cell migration and invasion." (PMID 27050378, 2016). "PI3K has also been shown to be involved in leptin-induced cancer proliferation." (PMID 27050378, 2016). "Leptin is largely produced by adipose tissue and cancer cells." (PMID 27050378, 2016). "In this study, we investigated, using both in vitro and in vivo experimental models, the ability of the synthetic FXR agonist GW4064 to interfere with cancer-promoting activities of CAFs focusing on the possible opposing role of activated FXR on leptin-induced breast tumor growth and progression." (PMID 26899873, 2016).
cancer (continued). "Noting the mutually antagonistic metabolic actions and other effects of leptin and ghrelin, the authors suggested the elevated ghrelin could be a protective mechanism to neutralize leptin and thus impede cancer progression." (PMID 27552970, 2016). "An additional way to abrogate leptin signaling in cancer is by targeting JAK/STAT pathway." (PMID 27472371, 2016). "Several antagonists of leptin signaling have been reported for cancer treatment." (PMID 27472371, 2016). "Data from many laboratories strongly suggest that leptin, one of the main adipokines secreted by the adipose tissue, plays an important role in the increased incidence, growth, recurrence and chemoresistance of several cancer types." (PMID 27472371, 2016). "In view of the prevalence of JAK/STAT3 hyperactivation in human cancers, and the potential role of leptin in these events, selective targeting of these proteins in cancer and cancer stem cells holds promise for significant advancement in the treatment of cancer." (PMID 27472371, 2016). "Leptin and its receptors are overexpressed in different human cancers." (PMID 27480179, 2016). "Leptin may drive BBC through maintaining cancer stem-like properties in orthotopically transplanted mice." (PMID 27042159, 2016). "However, a main feature of leptin signaling pathway is its crosstalk with several oncogenic signaling pathways that confer survival advantage to rapidly proliferating cancer cells." (PMID 27472371, 2016). "High levels of serum leptin may lead to aberrant intracellular signaling, which consequently results in cancer development." (PMID 27588409, 2016). "Existing prospective studies reporting the association between leptin and cancer have lacked external validity due to relative lack of racial diversity in the cohorts." (PMID 27636369, 2016). "Leptin has been reported to promote proliferation in various types of cancer cells." (PMID 27185268, 2016). "Current data suggest that inhibitors of leptin/JAK/STAT signaling could provide novel therapeutic strategies for cancer." (PMID 27472371, 2016). "It is a fact that leptin can induce cancer progression and tumor angiogenesis." (PMID 27472371, 2016). "Furthermore, the expression of SERPINE1 and MMP-2 was reduced in tumors formed with cancer cells and leptin shRNA obASCs, relative to tumors formed with cancer cells and control shRNA obASCs." (PMID 26286584, 2015). "Importantly, emerging evidence suggests that leptin plays an important role in cancer proliferation, invasion, and metastasis." (PMID 25948792, 2015). "Leptin suppresses apoptosis of cancer cells to induce tumor growth." (PMID 25704884, 2015). "In a subcutaneous transplanted tumor model, leptin even promoted the growth of cancer xenografts." (PMID 25948792, 2015). "Interestingly, leptin levels detected in the media of adipose tissue explants co-cultured with MC38 cancer cells were higher than in adipose tissue explants cultures, indicating cross talk between the adipose tissue and the cancer cells." (PMID 26472027, 2015). "Finally, the role of autophagy induction in leptin-induced cancer cell growth was confirmed by gene silencing of LC3B." (PMID 25704884, 2015). "Various research groups have been studying the oncogenic role of leptin in cancer." (PMID 26359358, 2015). "Leptin has been shown to stimulate proliferation in a variety of cancer cell lines." (PMID 25919692, 2015). "The deregulation of leptin and Ob-Rs has been shown in various cancers." (PMID 25948792, 2015). "Leptin has been reported to have different effects on cancer cell proliferation." (PMID 25948792, 2015). "Finally, to assess the effect of low and high ascites leptin levels, we supplemented the stemness selection medium with the ascites collected from obese and healthy BMI cancer patients." (PMID 26053184, 2015).
cancer (continued). "Along with low plasma leptin levels, animal models of cancer cachexia may also have an increased number of LRb receptors, which seems to be consistent with the severity of the body fat reduction present in this condition." (PMID 26508818, 2015). "The role of leptin signaling in cancer has been explored in various studies." (PMID 25948792, 2015). "In particular, growth-regulated protein (GRO), ENA-78/CXCL5, TIMP-2, and leptin were strongly up-regulated in malignant seroma, whereas IGFBP-1 (insulin-like factor binding protein-1), IL-3, IFN-γ, FGF-9 and IL-16 were down-regulated in malignant versus benign seroma fluid." (PMID 26361584, 2015). "A number of aging- and cancer-associated genes were observed among the 420 predicted bowhead-minke orthologs with dN/dS exceeding 1, including suppressor of cytokine signaling 2 (SOCS2), aprataxin (APTX), noggin (NOG), and leptin (LEP)." (PMID 25565328, 2015). "To further elucidate the molecular mechanisms underlying modulation of apoptosis by autophagy, we investigated whether autophagic process regulates apoptotic pathway by targeting Bax protein in leptin-treated cancer cells." (PMID 25704884, 2015). "In particular, enhanced serum leptin levels could play an integral role in cancer incidence as well as progression." (PMID 25704884, 2015). "Elevated leptin in cancer has been suggested to have several protumorigenic effects." (PMID 25019059, 2014). "Moreover, we found an independent correlation between ghrelin, obestatin, leptin and severity of cancer disease in our patients." (PMID 25400234, 2014). "Besides its well-known role in the regulation of satiety, leptin has been shown to activate a multi-functional signaling pathway involved in proliferation and cancer development." (PMID 25403445, 2014). "Recent studies suggested that leptin as a mitogenic factor might play an important role in the process of initiation and progression of human cancer." (PMID 25866478, 2014). "The activation at 24 h could be also explained by a general desensitisation to the signal as leptin signalling wears off and as metastatic cancer cells produce their own growth/proliferation factors." (PMID 25482303, 2014). "Systemic administration of high dose nanobody led to blockade of central actions of leptin and may compromise the anti-cancer effect of the nanobody." (PMID 24587106, 2014). "Taken all together, data strongly suggest that leptin signaling plays an important role in cancer development and/or progression that could be mechanistically linked to the upregulation of pro-angiogenic and pro-proliferative factors." (PMID 24202338, 2013). "As adipose tissue is an endocrine organ that produces and secretes polypeptide hormones (i.e., leptin and adiponectin), it has been hypothesized that imbalance of production of such hormones may be involved in cancer development." (PMID 24267900, 2013). "As are other cytokines, leptin is a ubiquitous and pleiotropic molecule, which is involved in a growing number of processes, i.e., energy balance, inflammation, reproduction, angiogenesis and cancer." (PMID 24202338, 2013). "However, accumulating evidence would suggest that leptin’s pro-angiogenic effects in cancer play an essential role in the disease." (PMID 24202338, 2013). "Leptin and adiponectin are two adipokines extensively studied in relationship to cancer." (PMID 24115945, 2013). "Overall, leptin plays roles in physiologic and abnormal angiogenesis atherosclerosis and cancer." (PMID 24202338, 2013). "Leptin also induced VEGF/VEGFR2 in other types of cancer cells." (PMID 24202338, 2013). "Leptin may promote cancer both directly and by increasing aromatase expression and estrogen production." (PMID 24115945, 2013). "In this meta-analysis, we found statistical evidence for a significant but week association of cancer risk with the LEP G2548A (or A19G) SNP but not with the LEPR Q223R SNP." (PMID 24146750, 2013).